KCNN3 (potassium calcium-activated channel subfamily N member 3)
Description:
Small conductance calcium-activated potassium channel that mediates the voltage-independent transmembrane transfer of potassium across the cell membrane through a constitutive interaction with calmodulin which binds the intracellular calcium allowing its opening. The current is characterized by a voltage-independent activation, an intracellular calcium concentration increase-dependent activation and a single-channel conductance of 10 picosiemens. Also presents an inwardly rectifying current, thus reducing its already small outward conductance of potassium ions, which is particularly the case when the membrane potential displays positive values, above + 20 mV. Activation is followed by membrane hyperpolarization. Thought to regulate neuronal excitability by contributing to the slow component of synaptic afterhyperpolarization (By similarity). [Isoform 3]: Does not function as a small conductance calcium-activated potassium channel (Probable). Selectively suppresses endogenous KCNN3 currents, in a dominant-negative fashion by decreasing the abundance of functional channels in the plasma membrane, possibly by selectively coassembling with and sequestering native KCNN3 protein in intracellular compartments. This dominant inhibitory effect extends to other members of the SK subfamily.
Synonyms: SK3; SKCa3; KCa2.3; hSK3; ZLS3
Tractability: Small molecule: a high-quality ligand is known; it belongs to a druggable protein family. Antibody: UniProt places it where antibodies can reach, with high confidence; its Gene Ontology location is reachable by antibodies, with high confidence; UniProt predicts a signal peptide or a membrane-spanning region; the Human Protein Atlas places it where antibodies can reach. PROTAC: ubiquitination databases record sites on it; its protein half-life has been measured; a small molecule that binds it is known.
Target class: Voltage-gated ion channel; Ion channel; Calcium-activated potassium channel; Potassium channels
Safety:
Unwanted effects reported when the protein is acted on. In parentheses: how it was acted on, where the effect was seen, and who reports it.
ataxia (activation, acute dosing; central nervous system, cardiovascular; source: Lynch et al. (2017))
convulsions (inhibition, acute dosing; central nervous system, cardiovascular; source: Lynch et al. (2017))
decreased convulsions (activation, acute dosing; central nervous system, cardiovascular; source: Lynch et al. (2017))
decreased locomotor activity (activation, acute dosing; central nervous system, cardiovascular; source: Lynch et al. (2017))
increased atrial refractory period (inhibition, acute dosing; central nervous system, cardiovascular; source: Lynch et al. (2017))
neurotoxicity (inhibition, acute dosing; central nervous system, cardiovascular; source: Lynch et al. (2017))
Gene: Protein-coding gene on chromosome 1 (154,697,455 to 154,870,281, reverse strand). Ensembl gene ENSG00000143603.
Subcellular location: Cell membrane; Cytoplasm, myofibril, sarcomere, Z line
Subcellular location (Human Protein Atlas): Cytosol; Plasma membrane
Pathways (Reactome):
Neuronal System: Ca2+ activated K+ channels
Gene Ontology:
Molecular function: calmodulin binding; inward rectifier potassium channel activity; small conductance calcium-activated potassium channel activity; calcium-activated potassium channel activity
Biological process: potassium ion transmembrane transport; potassium ion transport
Cellular component: plasma membrane; neuron projection; neuronal cell body; cytoplasm; membrane; Z disc
Genetic constraint (gnomAD): Loss-of-function variants: 16 observed, 64.15 expected, observed/expected ratio (o/e) 0.25, 90% interval 0.17 to 0.38. The upper end of that interval is the gene's LOEUF score, 0.38, which puts it in group 1 of 6, group 1 being the genes least tolerant of losing a copy. Missense variants: 597 observed, 995.71 expected, observed/expected ratio (o/e) 0.6, 90% interval 0.56 to 0.64. Synonymous variants: 370 observed, 411.63 expected, observed/expected ratio (o/e) 0.9, 90% interval 0.82 to 0.98.
Homologues: Orthologues: chimpanzee KCNN3 (99% identical), macaque KCNN3 (99% identical), guinea pig KCNN3 (97% identical), rat Kcnn3 (96% identical), mouse Kcnn3 (96% identical), pig KCNN3 (95% identical), rabbit KCNN3 (95% identical), dog KCNN3 (92% identical), Drosophila melanogaster SK (47% identical), Caenorhabditis elegans kcnl-2 (35% identical), Caenorhabditis elegans kcnl-1 (30% identical), Caenorhabditis elegans kcnl-3 (26% identical), and 2 more. Paralogues in human: KCNN2 (66% identical), KCNN1 (50% identical), KCNN4 (26% identical).
Diseases named in the same sentence as KCNN3 in open-access papers:
KCNN3 is named in the same sentence as 101 diseases in open-access papers, as found by Europe PMC text mining. Sharing a sentence is not in itself a finding about the gene and the disease. The quoted sentences say what the papers report.
schizophrenia (20 papers, 2005 to 2025). A major psychotic disorder characterized by abnormalities in the perception or expression of reality. "The KCNN3 is a schizophrenia potential risk gene that encodes a small conductance calcium-activated potassium channel (SK3) that regulates neuronal firing patterns." (PMID 35832186, 2022). "Of note, our previous study also showed evidence for the association of KCNN3 with schizophrenia through integrated analysis of GWAS with methylation QTL18." (PMID 33828182, 2021). "For instance, decreased predicted expression of the potassium channel KCNN3 was associated with schizophrenia." (PMID 32398653, 2020). "The expanded variant of KCNN3 has been reported to reduce channel conductance and is associated with better cognitive performance of individuals with schizophrenia." (PMID 24228761, 2013). "KCNN3, encoding the small conductance calcium-activated potassium channel SK3, is located at 1q21, a region reproducibly and strongly implicated in schizophrenia." (PMID 23675382, 2013). "Intriguingly, genes encoding potassium channels have already been implicated in the aetiology of schizophrenia, such as KCNN3 and recently KCNH2." (PMID 21629445, 2010). "Abnormalities in SK3 channel function may contribute to the risk of schizophrenia, as mutations in the KCNN3 gene are associated with dopamine neuron dysfunction as well as with risk of schizophrenia in some patient samples." (PMID 32701951, 2020). "The gene KCNN3 encoding SK3 channels contains a sequence of trinucleotide CAG repeats, which is associated with schizophrenia and bipolar disorders." (PMID 41465576, 2025). "KCNN3 contains two regions with CAG repeats with expansions reported in association with schizophrenia, and with earlier onset of the disease." (PMID 41164793, 2025). "Polymorphism of KCNN3, which reduces SK3 channel function, is associated with enhanced cognitive performance in schizophrenia patients." (PMID 31920555, 2019). "A growing body of evidence implicates several calcium and potassium channels in the susceptibility of schizophrenia, such as CACNA1C (Cav1.2 α subunit), KCNN3 (SK3), KCNH3 (Ether-A-Go-Go), and KCNJ3 (Kir3.1)." (PMID 31920555, 2019). "An association between the polymorphic CAG repeat length in the N-terminal coding region of KCNN3 and schizophrenia has also been questioned, but most results remain quite equivocal." (PMID 23675382, 2013). "KCNN3 CAG-tract length differences have been associated with anorexia and with schizophrenia and bipolar disorder but these associations are controversial." (PMID 17519034, 2007). "Downregulation of KCNN3, therefore, is consistent with overarching dopamine hypotheses related to schizophrenia, supporting its relevance for pathogenesis of the disorder." (PMID 32398653, 2020). "The gene KCNN3 encoding SK3 locates at 1q21, a chromosome closely related to schizophrenia." (PMID 31920555, 2019). "Finally, the SK3 gene, KCNN3, maps to chromosome 1q21, a region containing a major susceptibility locus for schizophrenia, and the polymorphic polyglutamine repeat within this gene is reportedly associated with this illness." (PMID 26803493, 2017). "In a meta-analysis of association studies for schizophrenia and bipolar disorder with the CAG-repeat length in KCNN3, the results demonstrated that the risks for both of these disorders were largely, if not entirely, independent of the CAG-repeat in the KCNN3 gene." (PMID 16162291, 2005). "Similarly, CAG long repeat expansions in the KCNN3 gene that affect the N-terminal region of the small conductance calcium-activated potassium channel KCNN3 (also known as hKCa3 or SK3) might be related to the pathology of schizophrenia and bipolar disorder." (PMID 29186753, 2017).
breast cancer (16 papers, 2012 to 2025). A primary or metastatic malignant neoplasm involving the breast. "Last, in breast cancer cells, σ1R is tightly associated to SK3 (KCNN3) and promotes the functional association of the K+ channel to Orai1 Ca2+ channels." (PMID 31780884, 2019). "KCNN3 is a calcium-activated potassium channel that has been shown to enhance tumor cell invasion in breast cancer and malignant melanoma." (PMID 30296942, 2018). "Breast cancer studies included E1 (KCNMB1), E4 (KCNN3), E9 (KCNH1, KCNK15), E15 (KCNT2), E22 (KCNK5, KCNK15), E33 (KCNQ1-OT1), E38 (KCNMA1), E48 (KCNJ9), and E63 (KCNK12)." (PMID 40867621, 2025). "To study the expression of AGPS and SK3 in breast cancers, we analyzed AGPS and KCNN3 mRNA (coding for SK3 protein) expressions in 50 invasive breast cancer biopsies (cohort 1)." (PMID 38642894, 2024).
atrial fibrillation (11 papers, 2013 to 2025). A disorder characterized by an electrocardiographic finding of a supraventricular arrhythmia characterized by the replacement of consistent P waves by rapid oscillations or fibrillatory waves that vary in size, shape and timing and are accompanied by an irregular ventricular response. "In this review, we will first give an overview of SK-channel function, its role in atrial fibrillation and outline pathophysiological mechanisms of KCNN3 risk SNPs." (PMID 38304423, 2024). "A genome-wide study has identified common genetic variants of KCNN3 that were associated with lone atrial fibrillation." (PMID 29636010, 2018). "Single nucleotide polymorphisms (SNPs) at chromosomes 4q25 (PITX2), 16q22 (ZFHX3), and 1q21 (KCNN3) have been shown to associate with atrial fibrillation (AF) in different genome-wide association studies (GWAS)." (PMID 28381281, 2017). "Calcium-activated K+ via its specific channels promotes action potential (AP) repolarization; accordingly, some KCNN2 and KCNN3 variants are associated with increased atrial fibrillation (AF) risk." (PMID 37372431, 2023). "Previous studies have suggested PITX2, KCNN3 and ZFHX3 as atrial fibrillation (AF) susceptibility genes." (PMID 28381281, 2017). "By downregulating, the expression of potassium calcium-activated channel subfamily N member 3(KCNN3) and SK3 and microRNA-499 (miR-499) affected the activity of the SK3 pathway and then triggered the occurrence of atrial fibrillation." (PMID 35387267, 2022).
prostate carcinoma (9 papers, 2018 to 2026). A carcinoma that arises from epithelial cells of the prostate gland. "KCNN3, which encodes a potassium calcium-activated channel, is a tumor-suppressor gene that has been observed to be downregulated in prostate cancer." (PMID 41516419, 2026). "A link between KCNN3, also known as SK3, and prostate cancer biology has been previously observed." (PMID 30296942, 2018).
Hypertension (8 papers, 2016 to 2025). The presence of chronic increased pressure in the systemic arterial system. "We revealed changes dependent on the hypertension model, since both KCNN4 and KCNN3 were downregulated in the aortas and mesenteric G3 arteries of SHR, whereas their expression levels were unchanged in DOCA-salt rats, with the exception of the KCNN4 level being enhanced in aortas." (PMID 34832902, 2021).
migraine (5 papers, 2005 to 2024). "A few ion channel markers, such as Kccn3 (potassium Calcium-Activated Channel Subfamily N Member 3) and Slc6a6 (sodium and chloride-ion dependent transporter) overlapped between mTBI, CSD and IS, where Kcnn3 has been associated with migraine pathology." (PMID 39578726, 2024). "This study provides evidence for association of variants in the KCNN3 ion channel gene with migraine susceptibility in the Norfolk genetic isolate with the rarer allelic variants conferring a possible protective role." (PMID 22030984, 2011). "To elucidate KCNN3 involvement in migraine, we performed gene-wide SNP genotyping in a high-risk genetic isolate from Norfolk Island, a population descended from a small number of eighteenth century Isle of Man ‘Bounty Mutineer’ and Tahitian founders." (PMID 22030984, 2011). "The Norfolk pedigree is a novel resource to evaluate KCNN3 gene involvement in migraine susceptibility." (PMID 22030984, 2011). "Association between KCNN3 polyglutamine repeat expansion length and migraine susceptibility has been demonstrated in two independent studies." (PMID 22030984, 2011). "This study undertook pedigree-based association testing to determine involvement of the KCNN3 gene in susceptibility to familial migraine in a unique isolated population from Norfolk Island." (PMID 22030984, 2011). "Additional analyses are required to determine if variants in KCNN3 are associated with migraine risk." (PMID 22030984, 2011). "A total of four intronic SNPs in the KCNN3 gene displayed significant association (P < 0.05) with migraine." (PMID 22030984, 2011). "This study provides evidence for association of multiple variants in the KCNN3 ion channel gene with migraine susceptibility in a large multigenerational pedigree from the unique Norfolk Island genetic isolate." (PMID 22030984, 2011). "Long (>19 repeats) and short (≤19 repeats) alleles: CAG repeat number in KCNN3; analysis performed utilising the comparison of long and short allele repeat numbers between migraine and control populations." (PMID 16162291, 2005). "This suggests that the common gene variants in KCNN3 may confer an increased risk of migraine in the Norfolk pedigree." (PMID 22030984, 2011). "To determine whether variants in the KCNN3 gene are associated with migraine risk, we utilised a small genetic isolate from Norfolk Island and performed a comprehensive 85 SNP analysis of this gene." (PMID 22030984, 2011). "Studies of additional variants in KCNN3 in the Norfolk pedigree are now required (e.g. polyglutamine variants) and further analyses in other population data sets are required to clarify the association of the KCNN3 gene and migraine risk in the general outbred population." (PMID 22030984, 2011). "The calcium-activated potassium channel gene (KCNN3; MIM602983) is in the vicinity of the FHM2 linked region on chromosome 1q21-23 region and proximal to a region linked to both FHM and typical migraine on chromosome 1q31." (PMID 22030984, 2011). "Studies of additional variants in KCNN3 in the Norfolk pedigree are now warranted, including the previously studied polyglutamine tracts to determine if these CAG repeats also show association with migraine in the Norfolk isolate." (PMID 22030984, 2011). "Although the phenotype was a highly penetrant, autosomal dominant form of MA, results provide compelling evidence that variants in other ion channel genes, in particular, potassium channels such as KCNN3, may influence more common, complex forms of migraine." (PMID 22030984, 2011). "Since FHM2-ATP1A2 is partly a potassium channel gene and is localised nearby to the potassium channel KCNN3, it may be interesting to investigate this gene in the common forms of migraine." (PMID 16162291, 2005). "Given that FHM2 maps to C1q23 and KCNN3 localizes nearby at C1q21.3, it may be important to examine the prevalence of the second (highly polymorphic) KCNN3 CAG polymorphism in populations affected and unaffected with migraine." (PMID 16162291, 2005).
migraine (continued). "The present association study tested whether length variations in the second (more 3') polymorphic CAG repeat in exon 1 of the KCNN3 gene, are involved in susceptibility to migraine with and without aura (MA and MO)." (PMID 16162291, 2005).
epilepsy (4 papers, 2010 to 2021). A brain disorder characterized by episodes of abnormally increased neuronal discharge resulting in transient episodes of sensory or motor neurological dysfunction, or psychic dysfunction. "Further analysis conducted on ATP1A2, SLC2A1, SLC2A2 KCNMA1 and KCNN3 showed they all are related to epilepsy or seizures." (PMID 27984588, 2016). "Thus, the combined decreased expression of Kcna3 (Kv1.3), Kcnk9 (TASK3), Kcnn3 (SK3), Kcng3 (Kv7.3), and Kcns3 (Kv9.3) around day 8 could lead to increased chances of persistent membrane depolarization, which ultimately may lead to epilepsy." (PMID 34877936, 2021). "None of the six individuals with dominant KCNN3 variant had epilepsy, although seizures could not be excluded in one patient." (PMID 33594261, 2021).
developmental delay (3 papers, 2021 to 2024). "Intellectual disability and developmental delay symptoms have been reported in patients carrying KCNN3 variants." (PMID 39569070, 2024). "The three individuals with dominantly acting KCNN3 variants showed moderate developmental delay or mild-to-moderate ID, coarse facial features, gingival enlargement, hypoplasia of distal phalanges, and aplastic or hypoplastic nails; two individuals had patent ductus arteriosus (PDA)." (PMID 33594261, 2021). "There is notable overlap in the phenotypic findings of these syndromes associated with dominant KCNN3, KCNH1, and KCNK4 variants, sharing developmental delay and/or ID, coarse facial features, gingival enlargement, distal digital hypoplasia, and hypertrichosis." (PMID 33594261, 2021).
heart failure (3 papers, 2014 to 2022). Inability of the heart to pump blood at an adequate rate to meet tissue metabolic requirements. "When comparing ventricular tissue from heart failure patients to non-diseased samples, we found significantly increased ventricular expression of KCNN3 in heart failure, as previously published." (PMID 33868017, 2021).
hypertrichosis (3 papers, 2021 to 2025). Excessive hair growth anywhere on the body. "Variants within KCNN3 have been associated with Zimmermann–Laband syndrome, which can be characterized by many phenotypes, including hypertrichosis, and NTN1 has roles in cochlear hair cell survival." (PMID 40725390, 2025). "Both features were consistently present in individuals with KCNK4 variant affecting function and variably present in patients with dominant KCNN3 (30% for hypertrichosis and 67% for gingival enlargement) or KCNH1 variant (19% for hypertrichosis and 79% for gingival enlargement)." (PMID 33594261, 2021). "Based on the data, the overarching phenotype associated with dominant KCNH1, KCNN3, and KCNK4 variants comprised DD and/or ID, hypotonia, coarsening facial features, gingival enlargement, and hypertrichosis." (PMID 33594261, 2021). "Similarly, all individuals with dominant KCNK4 variant (100%) had hypertrichosis, while only 3/16 (19%) and 3/6 (50%) with dominant KCNH1 and KCNN3 variant, respectively, showed hypertrichosis." (PMID 33594261, 2021).
ovarian carcinoma (3 papers, 2019 to 2024). A malignant neoplasm originating from the surface ovarian epithelium. "Another study reported that MIEN1, potassium calcium-activated channel subfamily N member 3 (KCNN3), and drug resistance in ovarian cancer are significantly associated with each other." (PMID 35582722, 2019). "In addition, higher KCNN3 mRNA expression levels were associated with a better prognosis in patients with ovarian cancer." (PMID 38480668, 2024).